CDK4 (cyclin dependent kinase 4)
Diseases named in the same sentence as CDK4 in open-access papers (continued):
Sharing a sentence is not in itself a finding about the gene and the disease.
tumor (continued). "Third, upon progression on CDK4/6i, multiple oncogenic pathways are likely to be mutated in the same tumor, stressing the need for novel therapies that can combine with oral SERDs and cell cycle inhibitors with tolerable toxicity." (PMID 38388477, 2024). "Here, we provide the first clinical evidence that CDK2 overexpression in CDK4/6-negative tumours is significantly linked with aggressive tumours and poor survival compared to tumours with low CDK2 and highly CDK4/6-expressing tumours." (PMID 38732271, 2024). "In the present study, we aimed to identify a panel of miRNAs assessed in tumor tissues which were associated with response to the combination of endocrine therapy (ET) and CDK4/6i palbociclib in patients with HR+/HER2−MBC." (PMID 38338777, 2024). "Some classical signaling pathways, such as PI3K and CDK4/6, are associated with a tumor mutational burden (TMB) state." (PMID 39544292, 2024). "Genotype cluster 2, rich in CDK4-amplified cells, associated with hypoxic and immune-rich environments in primary tumors switched to a tumor-enriched environment in recurrent tumors." (PMID 38805346, 2024). "In preclinical models, CDK4/6 inhibitors were associated with enhanced tumor antigen presentation, reduced proliferation of regulatory T cells (Tregs), and a lower expression of immune inhibitory receptors, such as PD-1." (PMID 38254885, 2024). "The p16 protein, encoded by the CDKN2A gene, functions as a tumor suppressor by inhibiting cyclin-dependent kinase 4, thereby preventing cell cycle entry into the S phase." (PMID 39376982, 2024). "In tumor tissues, seven gene amplification mutations included CDK4 (Mutation abundance, MA:1.57), AKT2 (MA:1.65), CCND2 (MA:1.63), MDM2 (MA:1.57), NTRK1 (MA:2.38), AXL (MA:1.65), and KRAS (MA:1.63), as well as the AFF3 gene missense (c.1781_1787del insC)." (PMID 37089080, 2023). "In some solid tumors, pharmacological inhibition of CDK4/6 has demonstrated substantial effectiveness, mostly by preventing Rb phosphorylation and causing G1 cell cycle arrest in tumor cells." (PMID 37240281, 2023). "To assess the potential CDK4/6i sensitivity of MKShi/ERSlo tumours, we examined the Rb loss-of-function signature (RBsig), which consists of E2F-associated genes and has been linked to poor prognosis and resistance to palbociclib." (PMID 37935787, 2023). "The enhanced production of PD-L1 by CDK4/6 inhibitors has now been linked to the stimulation of the transcription factor NF-kB in RB-proficient cell lines from various tumour types, as well as an increase in the protein’s durability." (PMID 36768557, 2023). "All Ifnar1−/− mice inoculated vector or Cdk4−/− MCA205 cells developed tumor masses at similar rates, indicating that type I interferon played a crucial role in anti-tumor effect induced by Cdk4-deficiency." (PMID 37833461, 2023). "Knockout of Sting is sufficient to reverse and partially reverse the anti-tumor effect of Cdk4 and Cdk6 deficiency respectively." (PMID 37833461, 2023). "We analyzed the main pathogenic pathways (MDM2 and CDK4), as well as the tumor microvascularization (CD31 and CD34) by immunohistochemical tests." (PMID 38132190, 2023). "More importantly, we have provided evidence that this CDK4/6-deficient triggered pathway plays an important role in enhancing anti-tumor immunity by CDK4/6 inhibitors." (PMID 37833461, 2023). "CDK6 is a key player in the cell cycle G1/S phase transition along with CDK4, and its aberrant activity and gene expression have been found to be associated with tumour progression in multiple human cancers." (PMID 37978493, 2023).
tumor (continued). "Despite current studies on the effect of CDK4/6 inhibition on anti-tumor immunity, most of them used CDK4/6 inhibitors, which can cause off-target effect." (PMID 37833461, 2023). "On the other hand, acquired resistance can arise due to acquired mutations in RB1 or CDK4/6, activation of other cell survival signaling pathways, or clonal selection of resistant tumor cells." (PMID 37176102, 2023). "While co-targeting cdk2 and cdk4/6 with endocrine therapy is promising in the pre-clinical setting, most of these approaches are associated with continued tumor proliferation and tumor relapse, and in most cases, failure to respond to treatment can be fatal." (PMID 37049472, 2023). "Loss of SMARCA4 also leads to downregulation of CD1, limits CDK4/6 activity in tumor cells, and affects sensitivity to CDK4/6 inhibitors." (PMID 37115343, 2023). "In actuality, HER2 targeted therapy-resistant recurrent tumor cells are susceptible to RNA interference or CDK4/6 inhibitor-mediated cyclin D1 down-regulation." (PMID 38293701, 2023). "High expression levels of TRIM28, H2AX or CDK4 were significantly associated with tumor recurrence in an independent cohort of HCC." (PMID 37870748, 2023). "Preclinical studies have shown that cell cycle arrest caused by CDK4/6 inhibition can elicit cellular senescence in multiple tumour types." (PMID 36127291, 2023). "We found that the 5-day-on/2-day-off palbociclib schedule caused a significant reduction in skeletal tumour burden at every timepoint measured, demonstrating that CDK4/6 inhibition can impede TNBC growth in bone." (PMID 37190140, 2023). "By forming Cyclin-CDK complexes, CDK4 also phosphorylates Rb, a tumour suppressor gene, causing it to become inactive and releasing all bound proteins, advancing tumour cells into the S phase." (PMID 37845675, 2023). "These patients already have genetic mutations in their tumor cells, allowing them to avoid the effects of CDK4/6 inhibitors and continue to proliferate in the presence of drugs." (PMID 38138549, 2023). "Unfortunately, none of these biomarkers showed clear promise, except for the rare tumor with complete Rb loss, which as expected, was resistant to CDK4/6i.14,15." (PMID 37567880, 2023). "Tumor cells with loss, or a low expression of RB are generally more resistant to CDK4/6 inhibitors than RB-proficient cells." (PMID 35892870, 2022). "Rb, a tumor suppressor, represents the primary target of CDK4/6i, and loss of Rb function, due to mutations or deletions, emerged in preclinical and clinical studies as a driver of both intrinsic and acquired resistance to CDK4/6i." (PMID 35330128, 2022). "Cdk4 gene ablation was associated with tumour death in genetically engineered KRAS-mutant NSCLC mouse models providing the preclinical rationale for CDK4 inhibition in NSCLC." (PMID 36284306, 2022). "Mouse studies have shown that overexpression of cyclin D or CDK4/6 increases susceptibility to breast cancer, while ablation induces tumor shrinkage in HER2+ and NSCLC tumor models." (PMID 35911672, 2022). "Such an approach would see the benefits of CDK4/6i-mediated transcriptional priming of T cells and tumor cells, while again potentially avoiding toxicities associated with continued CDK4/6i and ICI co-treatment." (PMID 35444175, 2022). "Considering the mechanisms of CDK4/6 inhibition, profound effect that causing tumor regression was rarely observed when CDK4/6 inhibitor was used as a monotherapy in HNSCC." (PMID 35546399, 2022). "It is well known that the major functions of the CDK gene family are involved in cell cycle regulation, and mutations often occur in human tumor cells, of which the most common is CDK4." (PMID 35193513, 2022).
tumor (continued). "Sema6C, a tumor suppressor in PC, causes reduction of cyclin D1 expression and cell proliferation which includes cyclin-dependent kinase 4/6(CDK4/6) by inhibiting the AKT/GSK3 signaling axis." (PMID 36713527, 2022). "A strong association between SF3B1 expression and key tumor -markers of development/progression (VEGFA/MKI67/EGFR/CDK4/PDGFRA) was found in GBM (CGGA- and Rembrandt-datasets), but not in the non-tumor samples (Rembrandt-dataset)." (PMID 35086552, 2022). "By upregulating both ICAM-1 and B7-2, along with MHC-I, CDK4/6 inhibitors thus render the tumor cells susceptible both to T cell killing and to certain types of NK cell killing." (PMID 35562811, 2022). "Together, these data show that FAK inhibition increases FAK nuclear localization leading to loss of CDK4/6 within tumor cells and leading to increased tumor cell apoptosis in vivo." (PMID 35525274, 2022). "Prior to treatment with ribociclib, patients’ tumor analyzations monitored cyclin D1/D3 amplification, CDK4/CDK6 amplification, CDK4/CDK6 mutations, and p16 mutations." (PMID 35884441, 2022). "It selectively inhibits CDK4/6 and arrests the associated tumor cells from moving from G1 to the S phase." (PMID 36744210, 2022). "CDK4 performs carcinogenic actions during initation and progression during and is implicated in the regulation of tumor processes in NSCLC." (PMID 37305398, 2021). "The activating mutation R24C of Cdk4 allows cells to overcome senescence and to acquire a proliferation phenotype by promoting the aberrant phosphorylation of Rb which inactivates its tumor suppressor function." (PMID 34232958, 2021). "The first CDK4 pan-cancer results suggest a close relationship between CDK4 performance and protein phosphorylation, clinical prognosis, tumor mutational load, immune cell infiltration, and gene mutation." (PMID 34422248, 2021). "CDK4 performs carcinogenic actions during initation and progression during and is implicated in the regulation of tumor processes." (PMID 37305398, 2021). "The loss of circ_0001588 significantly reduced HCC tumor growth in vivo by regulating miR-874 and CDK4." (PMID 34722778, 2021). "Tumor thickness (p = 0.0003) and the presence of regional lymph node metastasis (p = 0.015) were significantly associated with high CDK4 expression." (PMID 34395284, 2021). "Loss of PTEN and AKT1 amplification or AKT1 activating mutations in tumor samples have been associated with resistance to CDK4/6i." (PMID 34072070, 2021). "Genomic and transcriptomic studies revealed that amplification of cyclin D1 and CDK4 genes are associated with resistance to immunotherapy and that tumors with hyperexpression of genes promoting cell cycle display a “cold” immune tumor contexture." (PMID 34299136, 2021). "CDK4/6i mechanism of action is centered on Retinoblastoma protein (Rb), the product of the retinoblastoma tumor susceptibility gene (RB1), which is the main target of the CDK4/6-cyclin D complex and has a critical role in cell cycle regulation." (PMID 34072070, 2021). "CDK4/6 inhibitors promote tumor immunogenicity, and the effects of CDK4/6 inhibitors targeting both tumor T cells and regulatory T cells are associated with reduced activity of E2F transcription factors and DNA methyltransferase." (PMID 33364954, 2020).
tumor (continued). "Using a siRNA knockdown approach in combination with metformin treatment, we found that loss of CDK1/CDK4/CDK6 in combination with metformin exhibited enhanced antitumor properties in several tumor cell lines." (PMID 32811807, 2020). "Previous studies have shown that resistance to CDK4/6 inhibition is associated with a loss of ER/progesterone receptor (PR) expression in tumor biopsies of patients treated with the CDK4/6 inhibitor abemaciclib." (PMID 32344635, 2020). "For the tumor-associated genes ERBB2 and CDK4, amplifications were, respectively, found in 6 (15.4%) tumor samples of our cohort." (PMID 32083130, 2020). "Genes that are positively and inversely correlated with the CDK4/6-RB integrated signature define new tumor-specific pathways associated with RB-pathway activity." (PMID 32242058, 2020). "In our study, we used the immunohistochemistry to observe the association between the expression of ASPM and CDK4 in tumor tissue by uninterrupted slicing." (PMID 32742488, 2020). "NRAS, FGFR2, and ERBB2 have been associated to CDK4/6i resistance and/or antiestrogen resistance in whole exome analysis of tumor specimens." (PMID 32899866, 2020). "Cyclin‐dependent kinase 4 and 6 (CDK4/6) is a pivotal protein for cell cycle regulation, especially in phase G1 the mutation of which is closely related to the occurrence of tumour." (PMID 32881115, 2020). "The myelopreservation benefits of trilaciclib have been evaluated in patients receiving chemotherapy for the treatment of SCLC because SCLC tumour cells replicate independently of CDK4/6 due to the obligate loss of retinoblastoma." (PMID 33348420, 2020). "We focused on CDK1/CDK4/CDK6 given that increased expression of CDKs has been associated with many tumor types, and oral, highly selective CDKs inhibitor have already been developed." (PMID 32811807, 2020). "The p16INK4a encoded by CDKN2A is a tumor suppressor and inhibits CDK4 (cyclin-dependent kinase) influencing pancreatic β cell proliferation, through decreased cell mass and subsequent decreased insulin release." (PMID 33017871, 2020). "We noted that loss of Rb engenders resistance to CDK4/6 inhibitors, but it enhances the sensitivity of tumor cells to combined treatment with CB-839 and metformin." (PMID 30899002, 2019). "The encoded protein acts as a tumor suppressor by inhibiting the activity of cyclin-dependent kinase 2 or cyclin-dependent kinase 4 complexes, resulting in cell cycle blocks at G1." (PMID 30651718, 2019). "Addicted to an accelerated G1/S cell cycle progression, tumor cells with DEDD overexpression exhibit an increased susceptibility to the combinatorial treatment of cyclin-dependent kinases 4/6 (CDK4/6) and EGFR inhibitors." (PMID 31253784, 2019). "The upregulation of antigen processing and presentation-related genes is enriched, and serves as an underlying molecular mechanism of the anti-tumor immunity triggered by the CDK4/6 inhibitors in the animal models." (PMID 31023256, 2019). "Survival analysis revealed that overexpression of some oncogenes, such as EGFR, CDK6 or CDK4 were associated with poorer prognosis tumours." (PMID 31703248, 2019). "For a few variants, however, including NRAS Q22K and CDK4 R24C, and the MAFs in ctDNA, were higher or equivalent to the MAFs in tumor tissue, suggesting the subclonal expression of these mutations in the lesion sequenced." (PMID 31795494, 2019). "INK4a/p16 (encoded by CDKN2A) is a pan cancer tumor suppressor with a major anti-cancer role of G1 cell cycle arrest by inhibition of CDK4/6 (as part of the Cyclin D arm of the cell cycle/RB/E2F pathway)." (PMID 30890123, 2019). "In conclusion, we have demonstrated through our in vitro and in vivo studies that ribociclib is a highly selective CDK4/6 inhibitor that causes the G1 arrest of tumor cells containing intact Rb." (PMID 30443290, 2018).
tumor (continued). "Tumor cells often activate CDK4 to ensure proliferation, either by silencing genes that encode CDK4 antagonists or by enhancing CDK4 expression, e.g., through gene amplification." (PMID 30206211, 2018). "c-Myc also increases resistance of tumor cells to irradiation by regulating downstream genes such as cyclin-dependent kinase 4 (CDK4), ataxia-telangiectasia mutated kinase (ATM), checkpoint kinase 1 (Chk1), and Chk2." (PMID 29871674, 2018). "In contrast, somatic tumor-specific loss of CDKN2a/p16 results in constitutive CDK4/6 signaling associated with aberrant RB hyperphosphorylation." (PMID 30647837, 2018). "During the cell cycle, CDK4/6 inhibition has different effects but leads to the increase of tumour-associated mitochondrial mass via Rb and reactive oxygen species (ROS)." (PMID 30340359, 2018). "The downregulation of CDK4 expression mediated by miR-1 caused tumor cell cycle arrest in the G0/G1 phase, resulting in inhibited cancer cell proliferation." (PMID 28159933, 2017). "Mechanistic studies revealed that G0/G1 arrest and tumor senescence upon pulsed T treatment were associated with a marked decrease in cyclin D1, c-Myc and SKp2, CDK4 and p-Rb levels and upregulation of p27 and p-ERK1/2." (PMID 29371946, 2017). "This tumor suppressor gene encodes protein p16, which binds to cyclin-dependent kinase 4/6 (Cdk4/6) and arrests cell cycle in G1 phase." (PMID 26941789, 2016). "The combination of MEK and CDK4/6 inhibitors synergistically inhibited cancer cell growth in vitro and caused tumor regression in vivo in cell line and patient-derived xenograft models." (PMID 27167191, 2016). "CDK4 deficiency in mice can limit tumor cell proliferation either directly by affecting Rb phosphorylation in the tumor cell, or indirectly by preventing the elaboration of a growth permissive tumor microenvironment." (PMID 25803170, 2015). "Because a common oncogenic defect in basal-a/TNBC tumor cells is the loss of the retinoblastoma tumor suppressor (Rb1), a cytostatic CDK4/6 drugs that target Rb1 function was investigated as a mechanism to enhance the therapeutic window for Mps1 inhibition." (PMID 26398286, 2015). "Over expression of CDK4 has been shown in many tumour types including NSCLC, and has been implicated as a key factor in promoting the initiation and development of tumours." (PMID 26158863, 2015). "Palbociclib has been approved breakthrough therapy designation from FDA, however the molecular mechanisms underlying CDK4 inhibitor suppress tumor growth remain poorly define." (PMID 26697514, 2015). "This is of particular interest as high levels of CDKN2A (p16) protein, as seen in HPV-positive SCCHN, are associated with limited response to CDK4/6 inhibition in several tumor types." (PMID 26265441, 2015). "Genetic inactivation of p16INK4a following deletion or mutation of the gene encoding this structural inhibitor of CDK4/Cyclin D is one of the most frequent tumour suppressor mutations in human cancers and results in defective inhibition of CDK4." (PMID 25625291, 2015). "Based on the accumulating evidence that CDK4 gene alterations are associated with the proliferation of different tumor types, CDK4 inhibitors are currently being studied in clinical trials." (PMID 26528855, 2015). "Ribociclib is an orally bioavailable, highly specific CDK4/6i which causes cell cycle arrest and tumor growth inhibition in multiple Rb-proficient preclinical models." (PMID 26726315, 2015). "Treatment with PD-0332991 causes cell cycle arrest through CDK4/6 inhibition, leading to tumor suppression." (PMID 25136922, 2014). "In vivo, LY2835219 inhibits phosphorylation of Rb by CDK4/6 causing a G1 arrest resulting in antitumor activity in human tumor xenograft models." (PMID 24919854, 2014). "To evaluate the mechanism underlying the tumor-suppressing activity of fucoidan, we examined the expressions of p16INK4a, Cdk4/6 and pRb by western blotting in HepG2 cells after treatment with fucoidan for 24 h." (PMID 24807532, 2014).